ZNF253 (zinc finger protein 253)
Description:
May function as a transcription factor. Seem to have a transcriptional repression activity.
Synonyms: BMZF-1; BMZF1; ZNF411; FLJ90391
Tractability: PROTAC: ubiquitination databases record sites on it.
Gene: Protein-coding gene on chromosome 19 (19,865,881 to 19,894,674, forward strand). Ensembl gene ENSG00000256771.
Subcellular location: Nucleus
Pathways (Reactome):
Gene expression (Transcription): Generic Transcription Pathway
Gene Ontology:
Molecular function: DNA-binding transcription factor activity, RNA polymerase II-specific; RNA polymerase II cis-regulatory region sequence-specific DNA binding; sequence-specific DNA binding
Biological process: negative regulation of DNA-templated transcription; regulation of DNA-templated transcription; regulation of transcription by RNA polymerase II
Cellular component: nucleus
Genetic constraint (gnomAD): Loss-of-function variants: 5 observed, 9.8 expected, observed/expected ratio (o/e) 0.51, 90% interval 0.27 to 1.07. That is too few expected variants to judge how well the gene tolerates losing a copy. Missense variants: 473 observed, 592.76 expected, observed/expected ratio (o/e) 0.8, 90% interval 0.74 to 0.86. Synonymous variants: 193 observed, 201.72 expected, observed/expected ratio (o/e) 0.96, 90% interval 0.85 to 1.08.
Homologues: Orthologues: chimpanzee ZNF253 (99% identical). Paralogues in human: ZNF737 (74% identical), ZNF66 (73% identical), ZNF626 (72% identical), ZNF92 (69% identical), ZNF723 (67% identical), ZNF431 (67% identical), ZNF675 (66% identical), ZNF680 (65% identical), ZNF257 (64% identical), ZNF98 (64% identical), ZNF430 (63% identical), ZNF730 (63% identical), and 6 more.
Diseases named in the same sentence as ZNF253 in open-access papers:
ZNF253 is named in the same sentence as 2 diseases in open-access papers, as found by Europe PMC text mining. Sharing a sentence is not in itself a finding about the gene and the disease. The quoted sentences say what the papers report.
cancer (1 paper, 2025). A tumor composed of atypical neoplastic, often pleomorphic cells that invade other tissues. "The ZNF253 transcription factor shows cancer-tissue expression including lung, supporting a putative regulatory axis consistent with its reported motif activity in tumors." (PMID 41228248, 2025).
ZNF253 also shares sentences with these, for which no sentence is quoted: ovarian carcinoma (1 paper).